IGFBP5 (insulin like growth factor binding protein 5)
Diseases named in the same sentence as IGFBP5 in open-access papers (continued):
Sharing a sentence is not in itself a finding about the gene and the disease.
emphysema (2 papers, 2006 to 2021). "The causal role of QKI and IGFBP5 in the development of COPD/emphysema will need further investigation." (PMID 33823868, 2021). "QKI expression appeared to decrease according to % emphysema (n = 208; p = 0.0854), whereas, IGFBP5 expression significantly increased according to % emphysema (p = 0.0150)." (PMID 33823868, 2021). "Further, we determined whether QKI and IGFBP5 gene expressions in whole lung tissue correlated with emphysema severity." (PMID 33823868, 2021). "Fifteen genes were thus found to be upregulated in fibroblasts of emphysema, among them IGFBP-rP1 (4.9-fold), LOX (3.3-fold), LOXL2 (3.9-fold) and TIMP3 (3.0-fold), whereas 121 genes were downregulated, among them CDK4 (6.3-fold), FOSL1 (4.8-fold), OAZ1 (6.7-fold) and IGFBP-5 (5.3-fold)." (PMID 16504044, 2006).
endometriosis (2 papers, 2023 to 2025). The growth of functional endometrial tissue in anatomic sites outside the uterine body. "Despite the small sample number, there was evidence of differences associated with endometriosis at 210 consensus clusters, including IGFBP5, CALD1 and OXTR." (PMID 37443771, 2023). "However, a recent study found that IGFBP5 was significantly downregulated in a sub-population of stromal fibroblasts that was associated with endometriosis cases." (PMID 37443771, 2023). "IGFBP5 showed consistently low expression in endometrial stromal cells obtained from endometriosis patients." (PMID 37443771, 2023). "The potential for dysregulation of IGFBP5 to influence cell survival and proliferation highlight this gene as a good candidate for endometriosis." (PMID 37443771, 2023). "Of the 210 consensus clusters showing differential expression, 53 promoters passed Bonferroni correction, including genes (IGFBP5, OXTR CALD1) previously associated with endometriosis." (PMID 37443771, 2023).
esophageal cancer (2 papers, 2018 to 2022). A primary or metastatic malignant neoplasm involving the esophagus. "Similarly, in esophageal cancer, cisplatin resistant cells have lower IGFBP5 relative to cisplatin sensitive cells, and reintroducing IGFBP5 resulted in a 41% reduction in acquired cisplatin resistance." (PMID 36465383, 2022).
gastrointestinal stromal tumor (2 papers, 2022 to 2025). "A study in gastrointestinal stromal tumor models reported that silencing DOG1 significantly increased IGFBP-5 expression, and this increase may be related to suppression of the IGF pathway." (PMID 41303367, 2025). "DOG1 blockade delays xenograft growth and upregulates IGFBP5 in gastrointestinal stromal tumors (GIST), and imatinib resistant cells downregulate IGFBP5 mRNA." (PMID 36465383, 2022).
head and neck cancer (2 papers, 2011 to 2022). A primary or metastatic malignant neoplasm affecting the head and neck. "The cytosine-cytosine-adenosine-adenosine-thymidine (CCAAT)/enhancer-binding protein α and insulin-like growth factor binding protein-5, known suppressors of head and neck cancers, are upregulated by curcumin by activating p38 which leads to suppression of oral carcinogenesis." (PMID 35663647, 2022).
hepatocellular carcinoma (2 papers, 2010 to 2022). A malignant tumor that arises from hepatocytes. "Gankyrin has been shown to upregulate IGFBP5 expression in Huh-7 human hepatocellular carcinoma (HCC) and U-2 OS osteosarcoma cell lines." (PMID 36093095, 2022). "In Huh-7 human hepatocellular carcinoma (HCC) cells, Mybbp1a promotes the methylation of CpG islands within the IGFBP5 gene by binding to DNA methyltransferase 1 (DNMT1), thereby blocking IGFBP5 transcription." (PMID 36093095, 2022). "Two recent studies reported a high expression of IGFBP5 in hepatocellular carcinoma (HCC) and intra-hepatic cholangiocarcinoma (CC), suggesting that it has a similar role in vivo by promoting the survival of cancer cells." (PMID 20163708, 2010).
Hyperglycemia (2 papers, 2022 to 2024). An increased concentration of glucose in the blood. "This could explain the nucleosomal H3K4 preference we observe of Set7 methylation associated with IGFBP5 chromatin to directly regulate gene expression in response to hyperglycemia." (PMID 38630537, 2024). "The extent of hyperglycemia and body weight loss were similar between diabetic IGFBP5+/+ and IGFBP5−/− mice and non-diabetic mice." (PMID 35418167, 2022).
kidney cancer (2 papers, 2023 to 2024). Primary or metastatic malignant neoplasm involving the kidney. "IGFBP3 expression remained a marker of both kidney cancer and liver TECs, however, IGFBP5 expression was mainly seen in the kidney and not in liver NECs." (PMID 39516665, 2024).
liver disease (2 papers, 2022 to 2025). "It has been suggested that IGFBP5 in the blood of patients with NAFLD may signal the development of nonalcoholic steatohepatitis (NASH), a more severe liver disease, from NAFLD." (PMID 40699800, 2025). "The concentration of IGFBP5 in serum from NAFLD patients is positively correlated with fibrosis and steatosis in the liver and has been proposed to be a marker for progression from NAFLD to a more serious liver disease, non-alcoholic steatohepatitis (NASH)." (PMID 36465383, 2022).
lung disease (2 papers, 2018 to 2025). "We now show that IGFBP-5 expression is also significantly elevated in lung tissues and matching primary fibroblasts from patients with SSc-associated lung disease." (PMID 30374330, 2018).
metastatic tumor (2 papers, 2009 to 2025). "Within this list of genes in the metastatic tumor dataset, individual genes such as TMEM45A, IGFBP1, IGFBP5, and MALAT1 appeared to be associated with a worse patient survival." (PMID 40241258, 2025).
myocardial infarction (2 papers, 2024 to 2025). Gross necrosis of the myocardium, as a result of interruption of the blood supply to the area, as in coronary thrombosis. "First, further study should be carried out to identify the angiogenesis effect of IGFBP5 on improving myocardial infarction." (PMID 38886900, 2024).
neuropathies (2 papers, 2015 to 2023). "To study the role of the IGF1/IGFBP5/IGF1R system for axon maintenance, we investigated alterations of expression of IGFs and IGFBPs in peripheral nerves of patients with DNP and compared them with other neuropathies and healthy controls." (PMID 26025657, 2015).
Parkinson disease (2 papers, 2019 to 2023). A progressive degenerative disorder of the central nervous system characterized by loss of dopamine producing neurons in the substantia nigra and the presence of Lewy bodies in the substantia nigra and locus coeruleus. "Further, the BN models indicated that direct upstream regulators for the global parkinsonism score were miR-132, PHFtau-tangles, m434, and IGFBP5, and those for dexterity were VGF and miR-129-p5." (PMID 31582723, 2019).
preeclampsia (2 papers, 2019 to 2022). Preeclampsia is a hypertensive disorder of pregnancy that is characterized by new-onset hypertension with proteinuria presenting after 20 weeks of gestation, and depending on mild or severe forms may initially present with severe headache, visual disturbances, and hyperreflexia. "Many insulin-like growth factor-binding proteins were also in this cluster, such as Igfbp4 and Igfbp5, which have been associated with preeclampsia and extra-villous trophoblast invasion." (PMID 30795793, 2019). "For example, downregulation of DNA methyltransferase 3A (DNMT3A) results in increased IGFBP5 in patients with preeclampsia due to hypomethylation of the IGFBP5 promoter." (PMID 36465383, 2022).
sarcoma (2 papers, 2024 to 2025). A usually aggressive malignant neoplasm of the soft tissue or bone. "PTH1R encodes the parathyroid 1 receptor and, like IGFBP5, was also among the DEG upregulated in FUS/EWSR1-TFCP2 sarcoma compared with other RMS types." (PMID 38168093, 2024). "Third, PAPPA2, encoding the IGFBP5-specific proteinase pappalysin 2, was among the recurrently mutated genes in FUS/EWSR1-TFCP2 sarcoma." (PMID 38168093, 2024). "Whether the role of IGFBP5 in TFCP2-rearranged sarcoma depends on IGF signaling and is mediated via the full-length protein or proteolytic fragments remains to be determined." (PMID 38168093, 2024). "First, we found high expression of IGFBP5 in TFCP2-rearranged sarcoma." (PMID 38168093, 2024).
spinal muscular atrophy (2 papers, 2023 to 2024). A motor neuron disease that affect the muscles, and characterized by muscle weakness and atrophy resulting from progressive degeneration and irreversible loss of the anterior horn cells in the spinal cord (i.e., lower motor neurons) and the brain stem nuclei. "IGFBP5 has been shown to promote neuronal apoptosis in the experimental models and also in patients with spinal muscular atrophy and ALS." (PMID 39844875, 2024). "Conversely, in a recent study, increased expression of Igfbp5 was detected in skeletal muscle biopsies of spinal muscular atrophy (SMA) patients and non-SMA neuromuscular diseases." (PMID 36817606, 2023).
ulcerative colitis (2 papers, 2008 to 2025). An inflammatory bowel disease involving the mucosal surface of the large intestine and rectum. "IGFBP-5 expression is known to increase in ulcerative colitis, while IGF-1 and TGF-β1 expression is known to increase in both ulcerative colitis and Crohn's disease." (PMID 18928539, 2008).
vitiligo (2 papers, 2020 to 2024). Generalized well circumscribed patches of leukoderma that are generally distributed over symmetric body locations and is due to autoimmune destruction of melanocytes. "In all vitiligo individuals evaluated, we found that IGFBP5 levels were significantly increased compared with controls." (PMID 39337683, 2024). "IGFBP5, FOXO1, and WIF1 downregulation may indicate a loss of tolerance mechanisms or melanocyte regenerative capacity in the skin in canine VKH and vitiligo." (PMID 33384688, 2020).
acromegaly (1 paper, 2016). Acromegaly is an acquired disorder related to excessive production of growth hormone (GH) and characterized by progressive somatic disfigurement (mainly involving the face and extremities) and systemic manifestations. "Serum from the cat suffering from acromegaly contained significantly higher levels of IGF-I, IGFBP-3 and IGFBP-5 than serum from healthy and from diabetic cats." (PMID 27907059, 2016).
Airway obstruction (1 paper, 2021). Obstruction of conducting airways of the lung. "Further, an intergenic SNP of IGFBP5 (rs6435952) associates with airway obstruction." (PMID 33823868, 2021).
asthma (1 paper, 2017). "Regarding increased Igfbp3 and Igfbp5 levels in HDM-treated Igf1r-deficient mice, exogenous IGFBP3 and IGFBP5 administration blocks the physiological consequences of asthma and enhances epithelial cell adhesion to maintain the epithelial-mesenchymal boundary." (PMID 29272313, 2017).
autism (1 paper, 2025). Persistent deficits in social interaction and communication and interaction as well as a markedly restricted repertoire of activity and interest as well as repetitive patterns of behavior. "IGFBP family members including IGFBP5 are inversely associated with autism severity, and are potential peripheral biomarkers for numerous psychiatric disorders." (PMID 40649914, 2025).
bladder tumors (1 paper, 2017). "The IGF pathway is activated and therefore a potential therapeutic target for non muscle-invasive bladder tumors and IGFBP5 could be used as a surrogate marker for predicting tumor sensitivity to anti-IGF therapy." (PMID 28882129, 2017).
brain cancer (1 paper, 2023). A primary or metastatic malignant neoplasm affecting the brain. "However, the opposite pattern was found in brain cancer: IGFBP5 expression was higher in tumor tissues than in normal brain tissues, which indicated a potential protumorigenic role of IGFBP5 in brain cancer." (PMID 36949068, 2023).
carpal tunnel syndrome (1 paper, 2022). Entrapment of the median nerve in the wrist that is characterized by numbness, tingling and painful movement. "Next, we analysed the association of rs62175241 on DIRC3 and IGFBP5 expression in diseased tenosynovium samples from patients with carpal tunnel syndrome (n=77)." (PMID 36043126, 2022). "Considering that fibroblast proliferation is a histological feature of both trigger finger and carpal tunnel syndrome, we further investigated the effect of rs62175241 on IGFBP5 expression in fibroblasts." (PMID 36043126, 2022).
cerebral amyloid angiopathy (1 paper, 2018). "Conversely, cerebral amyloid angiopathy and insulin like growth factor binding protein 5 (IGFBP5) were only associated with APOE/TOMM40 SNPs (right lane), suggesting that the genetic effects of 457 SNPs on these variables are contingent on APOE/TOMM40." (PMID 30349450, 2018).
cervical squamous cell carcinoma (1 paper, 2024). A squamous cell carcinoma arising from the cervical epithelium. "IGFBP5 was downregulated in cervical squamous cell carcinomas tissues samples." (PMID 39060960, 2024).
chondrosarcoma (1 paper, 2019). A malignant cartilaginous matrix-producing mesenchymal neoplasm arising from the bone and soft tissue. "We provide evidence suggesting that TIMP3, IGFBP5, and BMP2 are direct targets of Gli-mediated Hh signaling with implications for chondrosarcoma pathology, including potential cross-talk between TGF-beta signaling and Hh signaling." (PMID 30695055, 2019).
Cirrhosis (1 paper, 2023). A chronic disorder of the liver in which liver tissue becomes scarred and is partially replaced by regenerative nodules and fibrotic tissue resulting in loss of liver function. "In addition, a positive correlation between IGFBP5 and myofibroblast marker gene levels was identified in human cirrhosis specimens." (PMID 38092723, 2023). "Moreover, a positive correlation between BRG1 expression and IGFBP5 expression was identified in human cirrhosis specimens." (PMID 38092723, 2023).
colitis (1 paper, 2022). Inflammation of the colon. "To explore the effect of IGFBP5 on the development of colitis, we evaluated the clinical scores according to weight loss, shape of stool and the degree of hematochezia." (PMID 36389828, 2022). "In this study, the functions of IGFBP5 on T cell subsets were evaluated in vitro, and the effect of IGFBP5 on immune Th17/Treg homeostasis in a DSS-induced colitis model of mice was assessed in vivo." (PMID 36389828, 2022). "The percentage of Th17 cells decreased and the percentage of Treg cells increased in the inflamed colon tissue and mesenteric lymph nodes of mice with colitis after IGFBP5 treatment." (PMID 36389828, 2022). "Our results of ELISA demonstrated that the serum levels of TNF-α, IL-1β and IFN-γ were increased in mice with DSS-induced colitis, but down-regulated after treatment with recombinant IGFBP5." (PMID 36389828, 2022). "Besides, there was an increased number of Th17 cells and a decreased number of Treg cells in colon tissue in mice with DSS-induced colitis, and IGFBP5 reversed the Th17/Treg imbalance, indicating an improvement in DSS-induced colitis." (PMID 36389828, 2022). "Moreover, the results of RT-qPCR showed that the expression of Igfbp5 decreased in mice with DSS-induced colitis." (PMID 36389828, 2022). "The results also proved that IGFBP5 regulated gut microbiota in DSS-induced colitis." (PMID 36389828, 2022). "IGFBP5 treatment significantly relieved the symptoms of colitis." (PMID 36389828, 2022). "Interestingly, we discover the expression difference of IGFBP5 between normal and colitis tissue using the typical inflammatory immune model-DSS induced experimental UC model in mice." (PMID 36389828, 2022). "Further results of animal experiments demonstrated that recombinant IGFBP5 reversed the imbalance of Th17/Treg and alleviated the severity of DSS-induced colitis." (PMID 36389828, 2022). "In present study, we studied the regulatory effect of IGFBP5 on T cell immune response in vitro, and the maintenance of Th17/Treg balance in vivo by using dextran sulfate sodium salt (DSS)-induced colitis in mice." (PMID 36389828, 2022). "Besides, the percentage of CD4+ CD25+ Treg cells in the mesenteric lymph nodes of mice with DSS-induced colitis was lower than that in normal group, while the percentage of CD4+ CD25+ Treg cells increased by recombinant IGFBP5 treatment." (PMID 36389828, 2022). "In addition, the results of histological examination and HAI indicated that IGFBP5 treatment alleviated colon damage and maintain the stability of intestinal epithelial structure in mice with DSS-induced colitis." (PMID 36389828, 2022).
COVID-19 (1 paper, 2024). A disease caused by infection with severe acute respiratory syndrome coronavirus 2. "IGFBP-5 expression was reduced in COVID-19 patients, and it is an inhibitor of angiogenesis and vascular smooth muscle cell proliferation." (PMID 38760690, 2024). "SerpinB5, ERRa, and IGFBP-5 in COVID-19 patients were all positively correlated with PTT, and most patients had measurement levels below healthy control subjects." (PMID 38760690, 2024). "SerpinB5, ERRa, and IGFBP-5 measurements in COVID-19 patients were mainly lower than healthy controls and exhibited a positive correlation with PTT; however, similar to PCMT1, none of the correlated proteins have been linked to thrombosis previously." (PMID 38760690, 2024). "Thus, the decreased expression of IGFBP-5, PF4V1, and SeprinA4 in COVID-19 may be cardioprotective, perhaps via suppression of angiogenesis and vascular transformation." (PMID 38760690, 2024).
cystinuria (1 paper, 2023). Cystinuria is a renal tubular amino acid transport disorder characterized by recurrent formation of kidneys cystine stones. "This includes the IGFBP5 gene candidate variant for bald thigh syndrome in sighthounds, SLC7A9 and SLC3A1 gene variants associated with cystinuria in Bulldogs, as well as PDK4 and TTN gene risk variants for dilated cardiomyopathy (DCM) in Dobermans." (PMID 36848397, 2023).
disc degeneration (1 paper, 2019). "We found that IGFBP5 was down‐regulated in human degenerative NP tissues and that its level was associated with the disc degeneration grade." (PMID 31290273, 2019). "In addition, the expression of IGFBP5 mRNA was negatively correlated with the disc degeneration grade (r = −0.72, P < 0.0001)." (PMID 31290273, 2019). "Moreover, the IGFBP5 expression level was significantly lower in degenerative NP tissues and was significantly correlated with the disc degeneration grade." (PMID 31290273, 2019).
epilepsy (1 paper, 2021). A brain disorder characterized by episodes of abnormally increased neuronal discharge resulting in transient episodes of sensory or motor neurological dysfunction, or psychic dysfunction. "We have shown that in KM rats, compared with W and “0” rats, there was a decrease in the transcription of the Igfbp5 and Gstm1 genes, the mutations of which were shown to increase the risk of developing epilepsy in humans." (PMID 34803604, 2021).
gastric adenocarcinoma (1 paper, 2020). "We identified THBS1, FN1, CALM1, COL4A1, CTGF, and IGFBP5 as potential inflammation-related targets for the treatment of gastric adenocarcinoma." (PMID 32801999, 2020).
gestational diabetes (1 paper, 2022). Carbohydrate intolerance first diagnosed during pregnancy. "Based on previously published transcriptional sequencing data, the mRNA level of IGFBP5 was increased in HUVECs in gestational diabetes compared to control HUVECs obtained from non-diabetic mothers." (PMID 35418167, 2022).